ATG5 (autophagy related 5)
Diseases named in the same sentence as ATG5 in open-access papers (continued):
Sharing a sentence is not in itself a finding about the gene and the disease.
hepatocellular carcinoma (50 papers, 2012 to 2025). A malignant tumor that arises from hepatocytes. "Deficiency of autophagic genes such as Beclin1 or Atg5 has been found in various cancers, including hepatocellular carcinoma (HCC), breast, ovarian, and prostate cancer." (PMID 34685734, 2021). "As a result of this study, it was suggested that serum Beclin-1 and ATG-5 could serve as novel biomarkers for predicting the risk of hepatocellular carcinoma." (PMID 40430125, 2025). "Although autophagy defects result in tumor formation, mosaic deletion of Atg5 in mice or Atg7 in mouse livers produces only benign hepatomas, suggesting that complete and specific autophagy deficiency promotes liver tumor initiation but restricts progression to malignant disease." (PMID 34829743, 2021). "Partial loss of ATG5 has also been observed in gastric and hepatocellular carcinomas." (PMID 29207660, 2017). "In contrast, another study conducted on 80 individuals, including a healthy control group, found that serum ATG-5 levels were significantly lower in individuals diagnosed with hepatocellular carcinoma compared to the control group." (PMID 40430125, 2025). "The miRNA hsa-miR-30a-5p was previously reported to be a tumour suppressor in lung squamous cell carcinoma by directly targeting the ATG5 gene an ad suppressor of hepatocellular carcinoma tumour migration and invasion by directly regulating SNAIL1." (PMID 39057123, 2024). "The most important polymorphisms in hepatocellular carcinoma were rs2241880 in ATG16L1, rs77859116, rs510432, and rs548234 in ATG5." (PMID 38353395, 2024). "For instance, TGF-β activates autophagy in human hepatocellular carcinoma cells by upregulating the levels of Beclin 1, Atg5 and Atg7." (PMID 36230955, 2022). "In hepatocellular carcinoma, ATG5 is a direct target of miR-30b and an indirect target of long noncoding RNA HNF1A-AS1." (PMID 32377431, 2020). "MiR-142-3p reduced sorafenib-induced autophagy through the downregulation of ATG5/ATG16L1 in hepatocellular carcinoma cells." (PMID 33082306, 2020). "For example, in human hepatocellular carcinoma cell lines, TGF-β induced the accumulation of autophagosomes and increased the expression levels of the autophagy markers Autophagy-related 5 (ATG5), Beclin1, ATG7 and death-associated protein kinase (DAPK)." (PMID 31195692, 2019). "Atg5-/- knockdown hepatoma cells were also manifested to be less effective in exhibiting the chemoresistance towards the cisplatin treatment." (PMID 26859293, 2016). "Previous reports showed that chimeric knockout of the autophagy gene Atg5 resulted in hepatomas in mice." (PMID 27655644, 2016). "Therefore, Wang and colleagues revealed that hepatocellular carcinoma progression is hastened by exosomal circTGFBR2 via an upregulation of ATG5-mediated protective autophagy." (PMID 39315094, 2024). "Furthermore, decreased expression of autophagy-related genes such as ATG5, ATG7, and Beclin-1 has been observed in hepatocellular carcinoma (HCC) cells, and our laboratory has confirmed that autophagy deficiency due to ATG5 knockout can induce malignant cellular transformation." (PMID 39519774, 2024). "Besides, ATG5 can be used as a target of lncRNA-ATB to affect the development of hepatocellular carcinoma by affecting autophagy." (PMID 34636718, 2021). "For example, apoptotic death of hepatoma cells expressing the oncogenic HBV X protein increases when autophagy is blocked, and the infection with Japanese encephalitis virus increases caspase activation and cell death in beclin-1 or Atg5-deficient cells." (PMID 24490870, 2014). "Autophagy inhibition via knockdown of mediators of autophagy, Beclin1 and ATG5, suppresses hepatocellular carcinoma (HCC) metastasis in mouse models." (PMID 40563926, 2025). "In hepatocellular carcinoma (HCC), elevated m6A modification of ATG5, driven by WTAP and recognized by YTHDC2, induces autophagy and promotes ferroptosis, thereby inhibiting HCC progression." (PMID 39695216, 2024).
hepatocellular carcinoma (continued). "Further, in hepatocellular carcinoma (HCC) lncRNA HNF1A-AS1 repressed autophagy by preventing the binding of miR-30b-5p to its target protein ATG5." (PMID 39716252, 2024). "Also, in hepatocellular carcinoma, ATG5 downregulation drastically dampened TGF-β2-induced EMT." (PMID 34901004, 2021). "In relation to autophagy, CAV1 appears to have an inhibitory role in hepatocellular carcinoma (HCC) since autophagy markers such as ATG5, Beclin-1, and LC3II were upregulated in HCCLM3-shCAV1 cells compared to mock cells." (PMID 31362353, 2019). "In a hepatocellular carcinoma (HCC) lung metastasis model, the inhibition of autophagy (via the lentivirus-mediated silencing of BECN1 and ATG5) markedly decreased the pulmonary metastasis of HCC cells." (PMID 25743109, 2015). "Inducing ferroptosis, facilitated by m6A modification of ATG5 mRNA mediated by WTAP and YTHDC2, effectively suppresses hepatocellular carcinoma development, highlighting a promising therapeutic approach." (PMID 39315094, 2024). "In human hepatocellular carcinoma cells, ELAVL1 regulates both autophagosome formation and autophagic flux via mediating translation of the autophagy-related genes (ATGs) ATG5 and ATG12." (PMID 38373797, 2024). "Furthermore, decreased expression of autophagic genes (Atg5, Beclin1, Atg7) and autophagic activity was observed in hepatocellular carcinoma (HCC)." (PMID 34440583, 2021). "Our results are in agreement with previous studies showing that TGF-β induces the expression of the autophagy-related genes BECN1, ATG5, and ATG7 through the SMAD signaling pathway in hepatocellular cancer cells, leading to the activation of autophagy." (PMID 34681055, 2021). "Combined with EGCG, doxorubicin played a concentration-dependent inhibitory role in autophagy signaling through increased Beclin-1 and Atg5 expression to inhibit autophagy and suppressed LC3 expression in hepatoma Hep3B cells." (PMID 32121322, 2020). "miR-181a was reported to repress autophagy in HCC by targeting pro-autophagic protein Atg5, leading to the reduction of apoptosis of HCC cells and acceleration of hepatoma growth." (PMID 33362215, 2020). "In another ferroptosis study in hepatocellular carcinoma, WTAP was investigated as a key factor upregulating ATG5 in an m6A-YTHDC2-dependent manner and targeted inhibition of WTAP may be an innovative and effective treatment strategy for HCC." (PMID 38638528, 2024). "Furthermore, a reduced expression of autophagy genes (ATG5, ATG7 and Beclin-1) has been observed in hepatocellular carcinoma (HCC) cells." (PMID 33743781, 2021). "The inhibition of autophagy by Atg5 silence increased the cytotoxicity of Timo AIII in hepatocellular cancer cells, which revealed the cyto-protective role of autophagy in Timo AIII-induced hepatocellular cancer cell death." (PMID 32581782, 2020). "Subsequently, wild type or Atg5 knock down hepatoma cells were pretreated with or without galectin-1, and then with cisplatin, after which their chemoresistance was evaluated." (PMID 26859293, 2016). "MiR-30a inhibits autophagy in chronic myeloid leukemia and hepatocellular carcinoma (HCC) cells by selectively blocking BECN1 and ATG5, which are needed for autophagy nucleation and elongation stages respectively." (PMID 38799506, 2024). "The finding that Atg5-/- or Atg7-/- mouse livers give rise to benign adenomas, but not malignant hepatocellular carcinomas, is likely indicative of the opposing roles that autophagy may plays at different stages of tumorigenesis." (PMID 23181220, 2012).
prostate carcinoma (49 papers, 2012 to 2025). A carcinoma that arises from epithelial cells of the prostate gland. "In our study, treatment of the Atg5-deficient DU145 prostate cancer cells, with the multi-tyrosine kinase inhibitor, sorafenib, induces mitochondrial damage, autophagy and cell death." (PMID 26416459, 2015). "We examined the frequency of Atg5 loss in prostate cancer patients by performing a tissue micro array and stained for intracellular Atg5 levels by immunohistochemistry." (PMID 26416459, 2015). "In the present study, we provide evidence that Atg5-deficient DU145 prostate cancer cells undergo caspase-independent, autophagic cell death in response to sorafenib." (PMID 26416459, 2015). "In addition to Beclin-1 and EI24, changes in the expression of Atg5 proteins and somatic mutations of the Atg5 gene are observed in gastrointestinal and prostate cancers." (PMID 32121322, 2020). "In response to sorafenib treatment in Atg5-deficient DU145 prostate cancer cells, formation of autophagosomes could promote interactions of p62 with RIPKs, leading to cell death via necroptosis." (PMID 29050220, 2017). "However, it remains to be established whether these predicted splicing defects lead to loss of protein expression and/or loss of function for ATG5 as observed in prostate cancer cells." (PMID 35585060, 2022). "Besides, some of the mutations in ATG5 genes found in the DU145 prostate cancer cell line may interfere its functions, such as binding with ATG16L1 and ATG5-ATG12 conjugation." (PMID 33926066, 2021). "Here, we showed that ATG5 and ATG7 are required for androgen-induced LDs in prostate cancer cells as KD of ATG5 and ATG7 prevented the formation LDs." (PMID 37874216, 2023). "Reciprocally, it has been reported that components of the autophagy machinery (MAP1-LC3, ATG5, ATG7) are required for LD biogenesis; MAPLC31 in prostate cancer cells and hepatocytes, ATG5 in mouse embryonic fibroblasts, ATG5 and 7 in adipocytes." (PMID 37874216, 2023). "Our study revealed that CHRM1 induces autophagy-mediated cell migration and invasion by targeting Atg5 in prostate cancer cells." (PMID 35720225, 2022). "In conclusion, the present findings indicated that autophagy induced by CHRM1 mediates migration and invasion targeting Atg5 via AMPK/mTOR pathway in prostate cancer cells." (PMID 35720225, 2022). "Silencing ATG5 or treatment with an autophagy inhibitor enhances Honokiol-induced apoptosis in prostate cancer cells." (PMID 35883843, 2022). "ATG5 is a potential target for upstream mediators in autophagy induction and enhancing prostate cancer progression." (PMID 35317831, 2022). "Downregulation of Atg5 inhibited cell autophagy in prostate cancer cells and the migration and invasion of prostate cancer cells." (PMID 35720225, 2022). "In contrast, a genetic knockdown of ATG5 and Beclin 1 was shown to mediate radioresistance in prostate cancer cells." (PMID 35989353, 2022). "When autophagy was blocked by knocking down the ATG5 gene, the decrease in the viability of the prostatic cancer cells was higher than that in the androgen ablation group." (PMID 33959154, 2021). "Knockdown of proteasomal catalytic subunits in human prostate cancer cells and immortalized mouse embryonic fibroblasts promoted autophagy activation and upregulated expression of ATG5 and ATG7." (PMID 34222330, 2021). "Here we reported that, in prostate cancer cells, the autophagy level was elevated under hypoxic condition, as well as the mRNA and protein level of ATG5, which is an important gene related to autophagy." (PMID 31700698, 2019). "Glutaminase (GLS) driven glutamine catabolism may promote radiosensitivity of prostate cancer by regulating redox status, dryness, and ATG5-mediated autophagy." (PMID 39588377, 2024). "In addition, we determined the effects of HCQ and BKM120 on the viability of the prostate cancer DU145 cell line, which is known to be naturally Atg5-deficient." (PMID 34844627, 2021).
prostate carcinoma (continued). "Finally, relevant to our initial observation that autophagy is elevated in urinary bladder and prostate cancer samples, we depleted either ATG5 or ATG7 in a human bladder carcinoma cell line T24 and in a human prostate cancer cell line PC-3." (PMID 31409894, 2020). "Similarly, expression of both LC3B and ATG5 were promoted by hypoxia in a HIF-1-dependent manner in gliomas or prostate cancer cells." (PMID 33488952, 2020). "Overexpression of HIF1α in PC-3 prostate cancer cells xenografts could increase tumor size and upregulate ATG5 expression." (PMID 31700698, 2019). "Taken together, our results, for the first time, proved that HIF1α could promote the proliferation and migration of PC-3 cells by direct upregulating ATG5 and autophagy level in PC-3 prostate cancer cells." (PMID 31700698, 2019). "Taken together, our results proved that HIF1α could promote the proliferation and migration of PC-3 cells by direct upregulating ATG5 and autophagy level in PC-3 prostate cancer cells." (PMID 31700698, 2019). "A recent study of prostate cancer demonstrated that the up-regulated expression of ATG5 might play a role in tumorigenesis." (PMID 26536662, 2015). "Also, analysis of androgen-independent prostate cancer cells showed that gossypol interrupted Beclin 1 and Bcl-2/Bcl-xL interactions and that gossypol-induced autophagy was dependent on Beclin 1 and Atg5." (PMID 22240779, 2012). "Finally, proteasome inhibition with bortezomib in human prostate cancer cells, and immortalized mouse embryonic fibroblasts promoted autophagy activation and upregulated expression of ATG5 and ATG7, which depended on phosphorylation of eIF2α, a downstream element of the PERK arm of the UPR." (PMID 34222330, 2021). "GZ17-6.02 was significantly better at killing MM cells than prostate cancer cells, and in both tumor types, knock down of ULK1, Beclin1 or ATG5 reduced both autophagosome formation and tumor cell killing." (PMID 38441437, 2024). "It is worth mentioning that co-administration of 3-methyladenine as an autophagy inhibitor, enhances the potential of abiraterone in prostate cancer suppression via inducing a further decrease in LC3, ATG5 and BECN1 levels compared to abiraterone alone." (PMID 35317831, 2022). "In prostate cancer suppression, abiraterone downregulates the expression levels of LC3, ATG5 and BECN1 to inhibit autophagy." (PMID 35317831, 2022). "Paclitaxel treatment has also been found to induce autophagy in A549 cells, U87 glioma cells, human PC-3 prostate cancer and colon HT-29 cancer cells via the increasing expression levels of LC3-II, ATG5 and Beclin1 in a dose-dependent manner." (PMID 34575981, 2021). "In a previous study, ER stress inducers activated the Beclin-1, Atg5, and LC3-II proteins and induced cell death in colon and prostate cancer." (PMID 34443626, 2021). "In prostate cancer stem cells, it represses mTOR, which is accompanied by an increase in the expression of ATG proteins, including ATG5, ATG7, ATG12 and Beclin1." (PMID 34575981, 2021). "Some researchers have found that down-regulation of ATG5 expression under hypoxic conditions can inhibit the expression of EMT markers N-cadherin and vimentin, thereby inducing malignant development of prostate cancer cells." (PMID 34636718, 2021). "The stimulated autophagy flux, and up-regulated expression of the autophagy-specific genes, ATG5 and ATG7 observed in some human prostate cancer cells." (PMID 29606130, 2018). "Increased expression of ATG5 has been observed in oral squamous cell carcinoma (OSCC) and prostate cancers." (PMID 29207660, 2017).
prostate carcinoma (continued). "Induction of autophagy-related genes ATG5 and ATG7 was observed at early time points after celastrol treatment in LNCaP prostate cancer cells." (PMID 26473737, 2015). "As opposed to that observed for ATG5, high tumour protein expression of ULK1 has been found to significantly associate with biochemical recurrence following radical prostatectomy of prostate cancer patients." (PMID 38910881, 2024). "To further validate the effect, we next used DU145 prostate cancer cells, which lacks functional autophagy due to the absence of Atg5." (PMID 36522339, 2022). "The identification of FOXO1 and ATG5/GLUT1 in purified stroma and their differential expression in aggressive vs. indolent prostate cancer samples indicate that it is possible to clinically categorize PCa in terms of the metabolic responses, namely RWE, that it elicits in the stroma." (PMID 27152194, 2016). "Furthermore, autophagy abolition through the ATG5/7 re-sensitized EC109/CDDP knockdown or the use of pharmacological inhibitors is greatly significant not only in the esophageal, but also in gastric, colorectal, bladder, ovarian, and prostate cancers." (PMID 32831056, 2020). "Of note, FQ also caused an increase in LC3-II levels in prostate cancer PC3 and PC3M cells but not in DU-145 cells lacking full-length autophagy-related gene 5 (ATG5) (which is essential for LC3 lipidation), suggesting the necessity of the functional autophagic lipidation machinery." (PMID 29162859, 2017). "MIR34A-loaded chitosan nanoparticles stimulate autophagy in prostate cancer cells independent of BECN1, ATG4, ATG5 and ATG7, known as non-canonical autophagy." (PMID 35317831, 2022). "Unlike, PC-3 and LNCaP cells, DU145 prostate cancer cells do not show ATG5 expression and consequently are unable to form functional ATG12–ATG5 conjugation complexes, resulting in an impairment of LC3 lipidation." (PMID 35585060, 2022). "Although it has been reported previously that autophagy might be induced upon treatment with BTZ or MZB, as demonstrated by increased expression of LC3 II, ATG5, and ATG7 in human prostate cancer cells, it has not yet been confirmed in other studies." (PMID 39204194, 2024). "Intriguingly, compared with PC-3 sh-NC cells, PC-3 sh-Atg5 cells failed to restore the expression of p-AMPK and p-mTOR even in the presence of CAR, indicating that CHRM1 activates AMPK/mTOR pathway by targeting Atg5 in the prostate cancer cells." (PMID 35720225, 2022).